KLHL21 (kelch like family member 21)
Description:
Substrate-specific adapter of a BCR (BTB-CUL3-RBX1) E3 ubiquitin-protein ligase complex required for efficient chromosome alignment and cytokinesis. The BCR(KLHL21) E3 ubiquitin ligase complex regulates localization of the chromosomal passenger complex (CPC) from chromosomes to the spindle midzone in anaphase and mediates the ubiquitination of AURKB. Ubiquitination of AURKB by BCR(KLHL21) E3 ubiquitin ligase complex may not lead to its degradation by the proteasome.
Synonyms: KIAA0469
Tractability: Small molecule: it belongs to a druggable protein family. PROTAC: ubiquitination databases record sites on it.
Gene: Protein-coding gene on chromosome 1 (6,590,724 to 6,614,607, reverse strand). Ensembl gene ENSG00000162413.
Subcellular location: Cytoplasm, cytoskeleton, spindle
Subcellular location (Human Protein Atlas): Centrosome
Pathways (Reactome):
Immune System: Antigen processing: Ubiquitination & Proteasome degradation
Metabolism of proteins: Neddylation
Gene Ontology:
Molecular function: cullin family protein binding; protein binding; ubiquitin-protein transferase activity; ubiquitin-like ligase-substrate adaptor activity
Biological process: chromosome passenger complex localization to spindle midzone; protein ubiquitination; regulation of cytokinesis; proteasome-mediated ubiquitin-dependent protein catabolic process
Cellular component: centrosome; Cul3-RING ubiquitin ligase complex; polar microtubule; cytoplasm; cytosol; spindle
Genetic constraint (gnomAD): Loss-of-function variants: 45 observed, 34.98 expected, observed/expected ratio (o/e) 1.29, 90% interval 1.01 to 1.65. The synonymous counts are far from expectation, so gnomAD's model fits this gene poorly and the ratio says little. Missense variants: 918 observed, 734.86 expected, observed/expected ratio (o/e) 1.25, 90% interval 1.18 to 1.32. Synonymous variants: 524 observed, 348 expected, observed/expected ratio (o/e) 1.51, 90% interval 1.4 to 1.62.
Homologues: Orthologues: chimpanzee KLHL21 (99% identical), macaque KLHL21 (99% identical), dog KLHL21 (97% identical), mouse Klhl21 (97% identical), guinea pig KLHL21 (96% identical), rat Klhl21 (96% identical), pig KLHL21 (94% identical), tropical clawed frog klhl21 (73% identical), zebrafish klhl21 (70% identical). Paralogues in human: KLHL30 (37% identical), KLHL24 (31% identical), KLHL29 (30% identical), KLHL17 (29% identical), KLHL35 (29% identical), KLHL5 (29% identical), KLHL12 (29% identical), KLHL20 (29% identical), KLHL2 (28% identical), KLHL38 (28% identical), KLHL4 (28% identical), KLHL6 (28% identical), and 42 more.
Diseases named in the same sentence as KLHL21 in open-access papers:
KLHL21 is named in the same sentence as 14 diseases in open-access papers, as found by Europe PMC text mining. Sharing a sentence is not in itself a finding about the gene and the disease. The quoted sentences say what the papers report.
breast carcinoma (4 papers, 2022 to 2025). "Laden with miR-660, they impede the tumor suppressor KLHL21, activating the NF-κB p65 pathway, which is key to enhancing breast cancer cell invasion and migration." (PMID 40485727, 2025). "A recent study uncovered that TAM-derived EVs enriched with miR-660 inhibit Kelch-like protein 21 (KLHL21) in breast cancer cells leading to the activation of NF-κB p65 signaling pathway." (PMID 38397187, 2024). "TAM-derived miR-660 competes with inhibitor kappa B kinase β (IKKβ) to bind kelch-like protein 21 (KLHL21), resulting in activation of NF-κB p65 signaling pathways, which lead to breast cancer progression." (PMID 35562884, 2022). "This disruption, primarily through the suppression of KLHL21 by miR-660 in TAM-EVs, not only accelerates breast cancer progression but also greatly increases the risk of lymph node metastasis." (PMID 40485727, 2025).
hepatocellular carcinoma (3 papers, 2016 to 2019). A malignant tumor that arises from hepatocytes. "Higher expression of KLHL21 is associated with poor hepatocellular carcinoma (HCC) prognosis." (PMID 30647843, 2018). "KLHL21 could affect cell migration and invasion, play an essential role in tumorigenesis and progression, and it might serve as a potential therapeutic target for cholangiocarcinoma and hepatocellular carcinoma." (PMID 31169496, 2019).
colorectal cancer (1 paper, 2024). A primary or metastatic malignant neoplasm that affects the colon or rectum. "This showed that the treatment of colorectal cancer cells with Lb. plantarum AY01 can correct the expression of FBXO32, KLHL21, and WDR34." (PMID 39132155, 2024). "FBXO32, KLHL21, and DYNC2H1 were significantly downregulated and WDR34 was significantly upregulated in colorectal cancer patients." (PMID 39132155, 2024).
glioma (1 paper, 2020). A benign or malignant brain and spinal cord tumor that arises from glial cells (astrocytes, oligodendrocytes, ependymal cells). "Klhl21 is known to bind E3 ubiquitin ligase through Cul3 and Klhl30 has been identified as a circadian pathway gene involved in the onset of glioma." (PMID 33043001, 2020).
melanoma (1 paper, 2020). A malignant, usually aggressive tumor composed of atypical, neoplastic melanocytes. "We therefore conclude that Mitf, a key regulator of melanocyte development and melanoma in vertebrates, seems to be an indispensable transcription factor for Klhl21/30 expression in Ciona, with Dmrt and Msx acting as potential co-factors." (PMID 33043001, 2020).
renal cell carcinoma (1 paper, 2024). "KLHL21 has emerged as a significant player in the ubiquitin ligase pathway, profoundly influencing renal cell carcinoma progression." (PMID 39428564, 2024).
retinitis pigmentosa (1 paper, 2022). Retinitis pigmentosa (RP) is an inherited retinal dystrophy leading to progressive loss of the photoreceptors and retinal pigment epithelium and resulting in blindness usually after several decades. "This study was extended to two other BTB-domain proteins, i.e., KLHL21, which regulates cell cycle and cell motility, and KLHL7, the mutations of which are involved in retinitis pigmentosa." (PMID 35563538, 2022).
uveitis (1 paper, 2025). An inflammatory process affecting a part of or the entire uvea. "For instance, in the uveitis only group, the genes KLHL21, MYLIP, ZNFX1, PDE4A, TNFRSF21, and N4BP2L2 were downregulated, while METTL72, GAPT, CD180, CCR2, and TLR7 were upregulated when comparing uveitis patients with healthy controls." (PMID 40270958, 2025).
cancer (4 papers, 2010 to 2024). A tumor composed of atypical neoplastic, often pleomorphic cells that invade other tissues. "Like many other Klhl members, Klhl21 is implicated in diverse types of carcinoma, probably due to its role in cell division." (PMID 33043001, 2020). "In mammalian cells, Klhl21 is thought to be involved in E3-ubiquitination during cytokinesis and regulation of cortical dynamics and is implicated in diverse types of carcinoma." (PMID 33043001, 2020). "More importantly, this quantitative approach identifies genes potentially involved in cancer that have not been previously identified, such as KLHL21, KIFC1, and XAB2." (PMID 20454660, 2010). "However, the role of KLHL21 in HCC remains unclear, despite its importance in other cancers." (PMID 39428564, 2024).
infection (1 paper, 2022). The state of being infected such as from the introduction of a foreign agent such as serum, vaccine, antigenic substance or organism. "In response to infection, in male mice, the TACC2, BUB1B, ATP5MC3, and MYO1E, and in female mice, the CAP1, MRPL2, COX5A, KLHL21, PDIA6, TSPO, and USP14 had direct interaction with TP-53." (PMID 35844510, 2022).
tumor (1 paper, 2016). "The average expression levels of VPS45, WIPI1, TTC1, IGBP1 and KLHL21 genes in all tested HCC tissues were greatly increased compared with those in the adjacent non-tumor tissues, showing the similar results to microarray data." (PMID 27769251, 2016).
KLHL21 also shares sentences with these, for which no sentence is quoted: Alzheimer disease (1 paper); cholangiocarcinoma (1); lung adenocarcinoma (1).